MYH16 (myosin heavy chain 16)
Description:
Has most probably lost the function in masticatory muscles contraction suspected for its homologs in dog (AC F1PT61) and apes.
Synonyms: MHC20; MYH16P; formerly MYH5
Gene: Protein-coding gene on chromosome 7 (99,272,839 to 99,311,132, forward strand). Ensembl gene ENSG00000293560.
Homologues: Orthologues: chimpanzee MYH16 (98% identical), dog MYH16 (95% identical). Paralogues in human: MYH6 (55% identical), MYH7 (55% identical), MYH1 (55% identical), MYH2 (54% identical), MYH3 (54% identical), MYH4 (54% identical), MYH8 (53% identical), MYH7B (53% identical), MYH13 (52% identical), MYH15 (45% identical), MYH9 (33% identical), MYH11 (32% identical), and 32 more.
Diseases named in the same sentence as MYH16 in open-access papers:
MYH16 is named in the same sentence as 3 diseases in open-access papers, as found by Europe PMC text mining. Sharing a sentence is not in itself a finding about the gene and the disease. The quoted sentences say what the papers report.
pancreatic adenocarcinoma (1 paper, 2021). "Like MGAT4EP, MYH16 is a cancer-testis unitary pseudogene, which was upregulated in solid tumors such as pancreatic adenocarcinoma (PAAD) and showed a much higher expression in testis than other normal tissues (data not shown)." (PMID 34425866, 2021).
MYH16 also shares sentences with these, for which no sentence is quoted: cancer (1 paper); cutaneous melanoma (1).